CFAP65 (cilia and flagella associated protein 65)
Description:
Plays a role in flagellar formation and sperm motility. Essential for acrosome formation, manchette organization, spermatid head morphogenesis and mitochondrial sheath assembly within the sperm flagellum during spermiogenesis (By similarity). Also required for proper assembly and stabilization of the C2a projection, a structural subunit of the central pair apparatus within the axoneme of motile cilia and flagella (By similarity).
Synonyms: CCDC108; DKFZp434O0527; MGC35338; SPGF40
Tractability: Antibody: UniProt predicts a signal peptide or a membrane-spanning region; its Gene Ontology location is reachable by antibodies, with medium confidence. PROTAC: ubiquitination databases record sites on it.
Gene: Protein-coding gene on chromosome 2 (219,002,846 to 219,041,527, reverse strand). Ensembl gene ENSG00000181378.
Subcellular location: Cell projection, cilium, flagellum membrane; Cytoplasmic vesicle, secretory vesicle, acrosome membrane; Cytoplasm; Cell projection, cilium, flagellum; Cytoplasm, cytoskeleton, cilium axoneme; Cytoplasm, cytoskeleton, flagellum axoneme
Gene Ontology:
Molecular function: protein binding; RNA binding
Biological process: acrosome assembly; cilium movement; flagellated sperm motility; sperm axoneme assembly; sperm mitochondrial sheath assembly; spermatogenesis
Cellular component: acrosomal vesicle; cytoplasm; sperm flagellum; sperm midpiece; axonemal central apparatus; acrosomal membrane; axoneme; motile cilium
Genetic constraint (gnomAD): Loss-of-function variants: 155 observed, 208.27 expected, observed/expected ratio (o/e) 0.74, 90% interval 0.65 to 0.85. The upper end of that interval is the gene's LOEUF score, 0.85, which puts it in group 3 of 6, group 1 being the genes least tolerant of losing a copy. Missense variants: 2,292 observed, 2,503.3 expected, observed/expected ratio (o/e) 0.92, 90% interval 0.88 to 0.95. Synonymous variants: 970 observed, 994.13 expected, observed/expected ratio (o/e) 0.98, 90% interval 0.93 to 1.03.
Homologues: Orthologues: chimpanzee CFAP65 (98% identical), macaque CFAP65 (95% identical), dog CFAP65 (74% identical), rabbit CFAP65 (72% identical), guinea pig CFAP65 (71% identical), pig CFAP65 (70% identical), rat Cfap65 (69% identical), mouse Cfap65 (69% identical), tropical clawed frog cfap65 (39% identical), zebrafish cfap65 (30% identical), Drosophila melanogaster Sox14 (4% identical), Drosophila melanogaster Sox21a (3% identical). Paralogues in human: SOX9 (5% identical), SOX5 (5% identical), SOX30 (5% identical), SOX6 (5% identical), SOX7 (5% identical), SOX17 (5% identical), SOX4 (4% identical), SOX8 (4% identical), SOX18 (4% identical), SOX3 (4% identical), SOX11 (4% identical), SOX10 (4% identical), and 8 more.
Diseases named in the same sentence as CFAP65 in open-access papers:
CFAP65 is named in the same sentence as 21 diseases in open-access papers, as found by Europe PMC text mining. Sharing a sentence is not in itself a finding about the gene and the disease. The quoted sentences say what the papers report.
male infertility (6 papers, 2020 to 2025). The inability of the male to effect fertilization of an ovum after a specified period of unprotected intercourse. "A new homozygous mutation in human CFAP65 (cilia and flagella associated protein 65) gene has been shown to cause male infertility as it generated multiple morphological abnormalities in sperm flagella." (PMID 32487021, 2020).
breast carcinoma (2 papers, 2015 to 2021). "Furthermore, ARHGEF1, CFAP65, PDGFRB and CLEC5A were labeled as prognostic marker by the Human Protein Atlas in renal and breast cancer, endometrial cancer, renal and urothelial cancer, and ovarian cancer, respectively." (PMID 34108011, 2021).
asthenospermia (1 paper, 2024). "Loss of cilia and flagella associated protein 65 (CFAP65), a transmembrane protein, led to severe asthenospermia and defects in the sperm head and cilium in male mice." (PMID 38246484, 2024).
autism (1 paper, 2022). Persistent deficits in social interaction and communication and interaction as well as a markedly restricted repertoire of activity and interest as well as repetitive patterns of behavior. "CFAP65 is a candidate gene for epilepsy, which appears to have some asserted genetic association to autism." (PMID 36310845, 2022).
colon cancer (1 paper, 2024). "Then we obtain a total of 135 genes are associated with CFAP65 in colon cancer by searching the UALCAN cancer database, and these genes were analyzed for GO enrichment using the clusterProfiler package." (PMID 38992586, 2024). "In terms of molecular functions and biological processes, genes were mainly concentrated in items related to cell motor activity and signal transduction, suggesting that CFAP65 may play an important role in cell motility potentially associated with metastasis of colon cancer." (PMID 38992586, 2024). "In conclusion, we demonstrate CFAP65 is a potential predictive marker for tumor progression in colon cancer." (PMID 38992586, 2024). "The expression of CFAP65 in colon cancer tissue was significantly higher than that in normal tissue, which is consistent with the TCGA data and the lab work result." (PMID 38992586, 2024). "The expression of CFAP65 was significantly higher in colon cancer tissue compared to paratumor tissue." (PMID 38992586, 2024). "CFAP65 is a potential prognostic marker for colon cancer, contributing to individualized evaluation and therapy for colon cancer patients." (PMID 38992586, 2024). "Subsequently, CFAP65 expression levels in colon cancer were evaluated by reverse transcription and quantitative polymerase chain reaction (RT-qPCR) and immunoblotting in 20 pairs of frozen samples, including tumors and their matched paratumor tissue." (PMID 38992586, 2024). "The area under curve (AUC) value is 0.616, indicating that the CFAP65 expression has a degree of prognostic value for colon cancer." (PMID 38992586, 2024). "Furthermore, protein expression of CFAP65 in 189 colon cancer patients were assessed via immunohistochemical staining." (PMID 38992586, 2024). "This study aimed to investigate the prognostic significance of CFAP65 in colon cancer." (PMID 38992586, 2024). "Furthermore, we found that CFAP65 (also known as CCDC108) is a strong prognostic factor affecting the overall survival and the disease-free survival of colon cancer patients, among a range of potential prognostic markers." (PMID 38992586, 2024). "To determine the expression level of CFAP65 in colon cancer and normal tissue, we detected CFAP65 expression in 20 pairs of frozen samples using both immunoblotting and RT-qPCR, finding that CFAP65 displayed a higher expression in tumors compared to their matched paratumor tissue." (PMID 38992586, 2024). "However, the biological function and clinical significance of CFAP65 in colon cancer remains unclear." (PMID 38992586, 2024). "Then we did not include samples from patients with advanced colon cancer, so the significance of CFAP65 for advanced colon cancer is still unclear." (PMID 38992586, 2024).
colorectal cancer (1 paper, 2024). A primary or metastatic malignant neoplasm that affects the colon or rectum. "Consequently, we will mainly focus on its molecular mechanism and the significance of CFAP65 in advanced colorectal cancer in the future research." (PMID 38992586, 2024).
Infertility (1 paper, 2024). "Alternatively, genes with no reported COI are enriched in gene sets associated with germ cell development and implicated in infertility mainly caused by spermatogenic failure (e.g., CATIP, CFAP65, CEP19) and oocyte/zygote/embryo maturation arrest (e.g., PADI6, REC114, WEE2)." (PMID 39202055, 2024).
Parkinson disease (1 paper, 2024). A progressive degenerative disorder of the central nervous system characterized by loss of dopamine producing neurons in the substantia nigra and the presence of Lewy bodies in the substantia nigra and locus coeruleus. "CFAP65 also plays a role in other diseases, for example, as a candidate gene for familial gastroschisis and Parkinson’s disease." (PMID 38992586, 2024).
sterility (1 paper, 2024). "CFAP65 is thought to play a critical role in the formation of cilia, mutation or dysfunction of which leads to male asthenoteratospermia and sterility." (PMID 38992586, 2024).
tumor (4 papers, 2012 to 2025). "Cox proportional hazard regression model was performed to analyze the independent prognostic factors affecting 5-year DFS rate, including age, histological differentiation, TNM stage, tumor location, mismatch repair deficiency, vascular invasion, and CFAP65." (PMID 38992586, 2024). "Furthermore, CFAP65 expression is independent of other clinicopathologic variables such as TNM stage and tumor location, suggesting that CFAP65 is an independent biomarker for assessing tumor progression risk." (PMID 38992586, 2024). "The cox hazard regression analysis model showed that CFAP65 expression, tumor stage and tumor location were independent prognostic factors." (PMID 38992586, 2024). "Specifically, TFAM knockdown, like ddC treatment, sequentially causes mtDNA depletion, calcium-mediated mitochondrial retrograde signaling, CFAP65 induction, and PCK1 induction, resulting in polygonalization and hypoproliferation of tumor cells." (PMID 29259235, 2017).
cancer (2 papers, 2024 to 2025). A tumor composed of atypical neoplastic, often pleomorphic cells that invade other tissues. "CFAP65 (cilia and flagella associated protein 65) is a fundamental protein in the development and formation of ciliated flagella, but few studies have focused on its role in cancer." (PMID 38992586, 2024). "Based on this speculation, we analyzed the proteins interacting with CFAP65, and found CFAP65 potentially play a role in cell movement and cancer invasion." (PMID 38992586, 2024).
CFAP65 also shares sentences with these, for which no sentence is quoted: ovarian carcinoma (2 papers); ciliopathy (1); endometrial cancer (1); epilepsy (1); gastric cancer (1); Hydrocephalus (1); Hydrolethalus (1); meningioma (1); primary ciliary dyskinesia (1); sarcoma (1).